SERPINB3 (serpin family B member 3)
Description:
May act as a papain-like cysteine protease inhibitor to modulate the host immune response against tumor cells. Also functions as an inhibitor of UV-induced apoptosis via suppression of the activity of c-Jun NH(2)-terminal kinase (JNK1).
Synonyms: SCCA-1; SCCA1; T4-A; HsT1196; SCC; SCCA-PD; SSCA1
Tractability: Antibody: its Gene Ontology location is reachable by antibodies, with high confidence.
Gene: Protein-coding gene on chromosome 18 (63,653,686 to 63,661,893, reverse strand). Ensembl gene ENSG00000057149.
Subcellular location: Cytoplasm
Subcellular location (Human Protein Atlas): Cytosol; Plasma membrane
Pathways (Reactome):
Immune System: Neutrophil degranulation
Gene Ontology:
Molecular function: cysteine-type endopeptidase inhibitor activity; protease binding; protein binding; serine-type endopeptidase inhibitor activity; endopeptidase inhibitor activity
Cellular component: cytoplasm; cytoplasmic vesicle; cytosol; extracellular exosome; nucleus; vesicle; azurophil granule lumen; extracellular region
Genetic constraint (gnomAD): Loss-of-function variants: 25 observed, 25.46 expected, observed/expected ratio (o/e) 0.98, 90% interval 0.71 to 1.37. The upper end of that interval is the gene's LOEUF score, 1.37, which puts it in group 5 of 6, group 1 being the genes least tolerant of losing a copy. Missense variants: 473 observed, 440.37 expected, observed/expected ratio (o/e) 1.07, 90% interval 1 to 1.16. Synonymous variants: 188 observed, 163.16 expected, observed/expected ratio (o/e) 1.15, 90% interval 1.02 to 1.3.
Homologues: Orthologues: mouse Serpinb3a (60% identical), mouse Serpinb3d (59% identical), rat Serpinb3 (59% identical), mouse Serpinb3b (58% identical), rat Serpinb3a (57% identical), mouse Serpinb3c (55% identical), tropical clawed frog serpinb4 (43% identical). Paralogues in human: SERPINB4 (92% identical), SERPINB13 (58% identical), SERPINB1 (49% identical), SERPINB12 (48% identical), SERPINB10 (46% identical), SERPINB6 (46% identical), SERPINB9 (45% identical), SERPINB11 (43% identical), SERPINB2 (43% identical), SERPINB8 (43% identical), SERPINB7 (40% identical), SERPINC1 (38% identical), and 24 more.
Diseases named in the same sentence as SERPINB3 in open-access papers:
SERPINB3 is named in the same sentence as 155 diseases in open-access papers, as found by Europe PMC text mining. Sharing a sentence is not in itself a finding about the gene and the disease. The quoted sentences say what the papers report.
cervical carcinoma (51 papers, 1995 to 2026). A carcinoma arising from either the exocervical squamous epithelium or the endocervical glandular epithelium. "IR in SERPINB3 deficient cervical carcinoma cells induces predominantly necrotic cell death, with biochemical and cellular features of lysoptosis." (PMID 35022555, 2022). "In our predictions, we found that SERPINB3 is associated with malignant tumors of the cervix and malignant neoplasms of the skin." (PMID 29949603, 2018). "Because Caski and SW756 cells are positive for HPV16 and HPV18, respectively, whether SERPINB3-induced chemokine expression is associated with HPV infection was examined using the HPV– cervical cancer cells C33A." (PMID 37279067, 2023). "In patients with cervical cancer or esophageal squamous cell carcinoma, high expression of SERPINB3 was associated with lymph node metastasis; however, the underlying causes are unknown." (PMID 37279067, 2023). "Additionally, SERPINB3 has recently been associated with poor prognosis in cervical cancer." (PMID 41362277, 2026). "Moreover, we show that the effect of SERPINB3 loss on radiation sensitivity in cervical tumor cells is similar if not greater than cisplatin, currently used as the standard of care to radiosensitize cervical cancer." (PMID 35022555, 2022). "The elevated expression of SERPINB3 within the neoplastic region suggests a potential mechanism for immune escape and treatment resistance in this subset of cervical cancer cells." (PMID 41362277, 2026). "The endogenous lysosomal cysteine protease inhibitor SERPINB3 (SCCA1) is elevated in patients with cervical cancer and other malignancies." (PMID 40297811, 2025). "Cervical cancers with higher levels of SerpinB3 secrete higher levels of chemokines that attract myeloid cells, which have an immunosuppressive activity through inhibition of T-cell activation, thus interfering with RT-induced antitumor immunity." (PMID 39061218, 2024). "We next examined the chemotactic response of human PBMCs, obtained from 7 patients with biopsy-proven cervical cancer prior to delivery of any treatment, to the chemokines secreted by tumor cells with high SERPINB3 expression." (PMID 37279067, 2023). "Patients with cervical cancer with high SERPINB3/SCCA expression had increased expression of phosphorylated STAT3 (p-STAT3) and CD11b." (PMID 37279067, 2023). "In the current study, we found that the mechanism of SERPINB3-mediated radioprotection in cervical cancer cells is inhibition of cell death." (PMID 35022555, 2022). "SERPINB3 has been found to be over-expressed in certain squamous epithelial cancers, such as uterine cervix carcinoma, head and neck carcinomas, and esophagus carcinoma." (PMID 25991924, 2015). "While high levels of SERPINB3 in the serum is associated with poor response to RT in patients with cervical cancer, it is not clear if SERPINB3 impacts radiation response on a cellular level." (PMID 35022555, 2022). "In vitro studies have shown that SerpinB3 protects neoplastic cells from apoptotic cell death through its interaction with Complex 1 of the mitochondrial respiratory chain and also through the inhibition of lysoptosis, conferring resistance to chemoradiation in cervical cancer." (PMID 37372056, 2023). "We hypothesized that SERPINB3 serves as a radioprotective factor in cervical cancer cells." (PMID 35022555, 2022). "Additional DEGs that were overexpressed in cluster 8 included several known canonical cervical cancer oncogenes – CDKN2A, SERPINB3, TP63, and KRT5." (PMID 41362277, 2026). "The expression of four different biomarkers, namely HMGB1, SCCA/SerpinB3, CEA, and CYFRA 21-1/Cytokeratin 19, in the serum of 36 cervical cancer patients was interpreted upon SDS PAGE and western blotting." (PMID 39583399, 2024). "To study the mechanistic link between SERPINB3 and chemokine expression, we genetically altered SERPINB3 levels in Caski and SW756 human cervical cancer cells and examined the effect on chemokine production." (PMID 37279067, 2023).
cervical carcinoma (continued). "SERPINB3/SERPINB4 has been found to be upregulated in a variety of cancer tissues, including esophageal cancer, cervical cancer, head and neck cancer, liver cancer, breast cancer, and so on." (PMID 36999136, 2023). "Cervical cancer cells lacking SERPINB3 are more sensitive to ionizing radiation (IR), suggesting that this protease inhibitor plays a role in the therapeutic response." (PMID 40297811, 2025). "KCP can also act positively on the downstream gene SERPINB3 and negatively on the downstream gene CEBPA to participate in the proliferative function of cervical squamous carcinoma cells and affect the resistance of cervical carcinoma to paclitaxel." (PMID 40297811, 2025). "We observed that KCP could act positively on the downstream gene SERPINB3 and negatively on the downstream gene CEBPA to affect the resistance of cervical carcinoma cells to paclitaxel." (PMID 40297811, 2025). "We then compared the effect of single gene knockout of SERPINB3 on radiosensitivity with or without cisplatin chemotherapy, the radiosensitizing agent used as standard of care for the treatment of patients with cervical cancer." (PMID 35022555, 2022). "Cervical cancer cells genetically lacking SERPINB3 are more sensitive to ionizing radiation (IR), suggesting this protease inhibitor plays a role in therapeutic response." (PMID 35022555, 2022). "According to the IPA analysis of differentially expressed genes, qPCR was used to verify KCP could also act positively on the downstream gene of SERPINB3 and negatively on the downstream gene of CEBPA to affect the resistance of cervical carcinoma to paclitaxel." (PMID 40297811, 2025). "The HPV subtype or positivity did not appear to be associated with SERPINB3 expression in our patient cohort, thus this may be a viable approach for patients with HPV- or non–HPV-associated cervical cancer." (PMID 37279067, 2023). "Therefore, we hypothesized that radiation, which causes both DNA damage and accumulation of oxidative species, might induce lysosomal membrane permeability in cervical cancer cells, particularly in cells lacking SERPINB3." (PMID 35022555, 2022). "Additionally, expression of wild-type but not the RSL-mutant B3-A341R protected SERPINB3-low cervical cancer cells from radiation further supporting the importance of an intact RSL to bait-and-trap target lysosomal proteases released from the lysosome after exposure to ionizing radiation." (PMID 35022555, 2022).
squamous cell carcinoma (48 papers, 2010 to 2025). A carcinoma arising from squamous epithelial cells. "For this reason, SERPINB3 and B4 have been regarded as important serum biomarkers used for the diagnostic and prognostic of squamous cell carcinomas." (PMID 25133778, 2014). "Initially identified as an oncogenic factor in squamous cell carcinomas, SerpinB3’s intricate involvement extends from fibrosis progression and cancer to cell protection in acute oxidative stress conditions." (PMID 39061218, 2024). "Diseases, including prostatic neoplasms, squamous cell carcinoma, esophageal neoplasms, mouth neoplasms, precancerous conditions and squamous cell carcinoma of esophagus had a strong connection with SERPINB3 and UMC4." (PMID 33790390, 2021). "The SERPINB3 gene is highly active in squamous cell carcinoma, but nearly undetectable or present at a low level in normal tissues." (PMID 32017381, 2020). "SERPINB3, -4, -6, and -13 were discovered as cathepsin inhibitors to promote tumor formation in squamous cell carcinomas and autoimmune diabetes." (PMID 32503295, 2020). "In the present study, we took advantage of the specific expression of the SERPINB3 gene in squamous cell carcinoma and constructed a pSERPINB3‐PE38KDEL toxin plasmid containing the SERPINB3 gene fragment as promoter by recombinant DNA technology." (PMID 32017381, 2020). "SERPINB3 was first discovered in squamous cell carcinoma of the cervix and it has been investigated in a variety of squamous cell carcinoma types." (PMID 25020046, 2014). "SERPINB3 was first identified in squamous cell carcinoma of the human uterus and, in chickens, it plays a crucial role in formation of egg yolk and egg white." (PMID 24098561, 2013). "Similarly, the human squamous cell cancer lines null for SERPINB3 were more sensitive than controls upon exposure to hypotonic stress." (PMID 35022507, 2022). "Since the discovery of the SERPINB3 (a.k.a. squamous cell carcinoma antigen (SCCA)) in 1977, numerous clinical reports show that elevated circulating levels of this protein are a poor prognostic factor for patients with advanced squamous cell carcinomas and other epithelial malignancies." (PMID 35022507, 2022). "Indeed, the overexpression of SERPINB3 in some types of squamous cell carcinomas, namely uterine cervix carcinoma, esophagus carcinoma, head and neck carcinomas, breast carcinoma and hepatocellular carcinoma is correlated with a poor prognosis." (PMID 25133778, 2014). "Squamous cell carcinoma antigen (SCC-Ag, also called SCCA, with isoforms SCCA1/SERPINB3 and SCCA2/SERPINB4) is a glycoprotein first isolated from squamous carcinomas and is widely studied as a serum tumor marker in cervical squamous cell carcinoma." (PMID 41464230, 2025). "The role of SERPINs in carcinogenesis was initially studied in squamous cell carcinoma (SCC) of the uterine cervix, in which SerpinB3 and B4 were first identified." (PMID 39061218, 2024). "This study utilized the specific expression of the SERPINB3 gene in squamous cell carcinoma and constructed the pSERPINB3‐PE38KDEL toxin plasmid with a SERPINB3 gene fragment used as a promoter by recombinant DNA technology." (PMID 32017381, 2020). "SERPINB3 (SB3), previously known as Squamous Cell Carcinoma Antigen 1 (SCCA1), a member of the ovserpins/clade B serpin family, was originally purified from squamous cell carcinoma of the uterine cervix." (PMID 24810714, 2014).
lung carcinoma (45 papers, 2017 to 2025). "Of note, SERPINB3 is also expressed in lung cancer and is negatively associated with prognosis, providing credence to this model." (PMID 37279067, 2023).
hepatocellular carcinoma (25 papers, 2008 to 2025). A malignant tumor that arises from hepatocytes. "Recently, a study clearly showed that hepatocellular carcinoma cells overexpressing SerpinB3 are more resistant to Sor treatment, and was associated with the activation of caspase signaling." (PMID 36285158, 2022). "In conclusion, in patients affected by hepatocellular carcinoma, the pattern characterized by p66shc downregulation and elevated SerpinB3 levels was associated with markedly better survival." (PMID 33922660, 2021). "In the present study we have demonstrated that the nuclear localization of Myc was strongly associated with the presence of SerpinB3, both in hepatocellular carcinoma and in different experimental models." (PMID 26634820, 2015). "Of note, the expression of TGF-β and SerpinB3 has been related to the activation of the WNT/β-catenin pathway in both hepatocellular carcinoma (HCC) and colorectal cancers, associating with more aggressive tumors, with an earlier recurrence and a worse prognosis." (PMID 39061218, 2024). "The compound 1-PPA was able not only to suppress PAR2 and SerpinB3, but also C/EBP-β transcription in hepatoma cells over-expressing SerpinB3." (PMID 38307387, 2024). "In hepatoma cells, Wnt co-receptors LRP-5/6 and LRP-1, implicated in cell survival and invasiveness, were upregulated by SerpinB3." (PMID 37372056, 2023). "The protease inhibitor SerpinB3 (SB3) has been identified in several malignancies including hepatocellular carcinoma." (PMID 34478594, 2022). "Given the available evidence that SERPINB3 expression in many other cancers including epithelial cancers of the head and neck, anus, lung, esophagus as well as hepatocellular carcinoma carries a similar poor prognosis, we expect this to be the case." (PMID 35022555, 2022). "In this study we have analyzed the relationship between p66shc and SerpinB3 expression in hepatocellular carcinoma in relation to clinical outcome and its potential involvement in cell death." (PMID 33922660, 2021). "Tumors originating from hepatoma cells overexpressing SerpinB3 showed typical features of necroptosis." (PMID 33922660, 2021). "In patients with hepatocellular carcinoma the best survival was observed in the subgroup with p66shc levels below median values and SerpinB3 levels above median values." (PMID 33922660, 2021). "The aim of the study was to evaluate the expression of the pro-apoptotic p66shc and the anti-apoptotic SerpinB3 molecules in relation to clinical outcome in patients with hepatocellular carcinoma and to evaluate their effect on cell fate and tumor growth." (PMID 33922660, 2021). "Proliferation and cell death markers were analyzed in hepatoma cells overexpressing SerpinB3, under different stress conditions." (PMID 33922660, 2021). "These EV preparations showed a significantly higher protection from H2O2 induced oxidative stress in both the hepatoma cell line and in primary cardiomyocytes, compared to cells treated with naïve EVs or SerpinB3 alone, used at the same concentration." (PMID 34451800, 2021). "Mice p66shc knockout showed high levels of SerpinB3, while in hepatoma cells overexpressing SerpinB3, p66shc expression was trivial." (PMID 33922660, 2021). "SerpinB3 is a hypoxia- and hypoxia-inducible factor-2α-dependent cystein protease inhibitor that is up-regulated in hepatocellular carcinoma and in parenchymal cells during chronic liver diseases (CLD)." (PMID 28611447, 2017). "Results from this study indicate that Myc was up-regulated by SerpinB3 through calpain and Hippo-dependent molecular mechanisms in transgenic mice and hepatoma cells overexpressing human SerpinB3, and also in human hepatocellular carcinomas." (PMID 26634820, 2015). "Of relevance, Yap mRNA levels were increased not only in transfected hepatoma cells, but also in human HCCs specimens with high SerpinB3." (PMID 26634820, 2015).
hepatocellular carcinoma (continued). "To assess the functional impact of decreased Yap expression in the transcriptional modulation of Myc gene exerted by SerpinB3 in hepatoma cells, we knocked down Yap gene by lipofectamine transduction of siRNA." (PMID 26634820, 2015). "Liver tumors with stemness signatures are highly aggressive, and in hepatocellular carcinoma (HCC), the subset of more aggressive tumors, characterized by early recurrence after surgical resection, have shown the highest levels of SerpinB3, associated with high β-catenin and TGF-β1 expression." (PMID 38201652, 2024). "Additionally, PFGS combined with Sor markedly inhibited cell proliferation and invasion and activation of the NF-κB/HIF-2α/SerpinB3 pathway in Sor-resistant hepatoma cells compared with a single treatment." (PMID 36285158, 2022). "Hepatoma cells overexpressing SerpinB3 were more prone to die after oxidizing treatments." (PMID 33922660, 2021). "SERPINB3 is highly expressed in tumors of epithelial origin, including hepatocellular carcinoma." (PMID 29949603, 2018). "Also, SERPINB3, which is over-expressed in human hepatocellular carcinoma, has been shown to induce apoptosis resistance, epithelial-to-mesenchymal transition and increasing cellular invasion." (PMID 24710357, 2014). "SERPINB3 is a cysteine-proteases inhibitor up-regulated in a significant number of cirrhotic patients carrying hepatocellular carcinoma (HCC) and recently proposed as a prognostic marker for HCC early recurrence." (PMID 25544768, 2015). "As well, recent evidence suggests that elevated expression of SERPINB3 together with SERPINB4 is not limited to cancers of squamous origin but also extends to adenocarcinoma of the lung, breast, and pancreas, as well as hepatocellular carcinoma." (PMID 40869249, 2025). "By contrast, SerpinB3 can induce HIF-2α stabilization through direct NEDDylation and this has been suggested to promote proliferation of liver cancer and to favor hepatocellular carcinoma progression." (PMID 38307387, 2024). "SerpinB3 (SB3) is a serine protease inhibitor up-regulated in several malignancies of epithelial origin, including hepatocellular carcinoma (HCC)." (PMID 31817100, 2019). "SerpinB3 is a serine protease inhibitor, which is not detectable in normal hepatocytes and has been found progressively upregulated in liver cirrhosis, dysplastic nodules, and hepatocellular carcinoma." (PMID 36285158, 2022). "Researchers detected high levels of SERPINB3 expression in primary liver tumors but not in normal liver tissue and showed a significant correlation with transforming growth factor-β1 and cytoplasmic β-catenin expression in hepatocellular carcinomas with poor prognoses." (PMID 27167107, 2016). "This study focused on determining the anticancer effect of paeoniflorin and geniposide mixture (PFGS) combined with sorafenib (Sor) in hepatocellular carcinoma (HCC) and, in particular, whether PFGS increases the antitumor effect of Sor by modulating the NF-κB/HIF-2α/SerpinB3 pathway." (PMID 36285158, 2022).